ALB (albumin)
Diseases named in the same sentence as ALB in open-access papers (continued):
Sharing a sentence is not in itself a finding about the gene and the disease.
tumor (continued). "Furthermore, the present study does not evaluate a larger number of different tumour markers (e.g., CA 15-3, CA 19-9, PSA, etc.) or compare their diagnostic utility with more classical laboratory tests (e.g. LD, albumin etc.)." (PMID 29472801, 2018). "Several studies, including studies of TPP-docetaxel conjugates and TPP-photosensitizer-loaded albumin nanoparticles, paclitaxel, cisplatin or Dox-α-TOS conjugate-loaded lipid nanoparticles, and DQA-Dox-loaded pH-responsive micelles, have revealed dual-targeting to the tumor area and mitochondria." (PMID 30174604, 2018). "At the 38th week, there was a significant elevation of total protein in group V although the albumin was not elevated which could be due to the ability of HCC to uniquely synthesize various tumour-related proteins which act as biomarkers." (PMID 28372475, 2017). "Subsequently, radiolabeling of DOTA- or NOTA-attached albumin and anti-IGSF4 antibody (an anti-tumor-targeting antibody) with [67Cu], a β−-emitting radionuclide, could be achieved in a highly efficient manner via a simple chelation with DOTA proving to be a more superior chelator than NOTA." (PMID 28507297, 2017). "In contrast, there was not a significant correlation between the serum level of LDH and tumour location, age, sex, Karnofsky performance status (KPS), metastasis (intrahepatic or extrahepatic), location of intrahepatic metastasis (right, left or both lobes), albumin or PLR." (PMID 28345594, 2017). "In addition, there were minimal changes in MR signal intensity and in T1 values in the C6 tumor region after administration of control probes, namely, non-Ab albumin-Gd-DTPA and a normal rat IgG-Gd-DTPA." (PMID 28485003, 2017). "However, symptomatic diagnosis, LMR, tumor size, tumor location, albumin, age, CA199, CEA, AFP, CA125 and ECOG-PS were not significant predictors of DFS." (PMID 29235538, 2017). "Albumin can also be accumulated in solid tumors by the enhanced permeability and retention (EPR) effect; however, our approach was intended to increase the cellular uptake of drug-loaded nanocarriers rather than to enhance the accumulation of nanocarriers in the tumor extracellular microenvironment." (PMID 27068794, 2016). "To test the ‘stromal barrier' hypothesis, we treated tumour-bearing KPCY mice with standard of care chemotherapy—the nucleoside analog gemcitabine (GEM) and the albumin-bound microtubule inhibitor nab-paclitaxel (PTX)—to examine the effects of chemotherapy on metastasis." (PMID 27628423, 2016). "Similarly, univariate analysis in the primary cohort showed that serum-CEA, -CA199, -ALB, -GGT, -ALT, -ALP, tumor size, TNM, and MRP8/MRP14 ratio combination were predictors for OS; serum-ALB, -ALP, tumor size, TNM, and MRP8/MRP14 ratio combination were predictors for TTR." (PMID 26472105, 2015). "Furthermore studies have demonstrated that albumin has a shorter half-life and a higher turnover in tumor-bearing mice, despite a compensatory increase in hepatic albumin synthesis, compared to non-tumor-bearing mice." (PMID 25161624, 2014). "In this study we complexed fenretinide with Human Serum Albumin [HSA] with the aim to enhance its bioavailability through an improvement of its aqueous solubility and to exploit the Albumin affinity to cav-1 to favour the uptake of the complex in the tumor cells expressing high levels of cav-1." (PMID 25015569, 2014). "Although the albumin-serum content was 20% higher in group L (under nutritional supplementation) than in group C, the leucine-rich diet did not prevent the reduction in albumin levels in the foetuses from tumour-bearing rats, as observed when comparing the LW and L groups (P < 0.0001)." (PMID 24383706, 2014). "Albumin conjugation of SN38 represented both higher and maintained level of blood concentration for up to 4 h in comparison to that of free SN38 that led to improvement of passive tumor targeting due to the EPR effect and consequently enhanced the antitumor efficacy." (PMID 24895635, 2014).
tumor (continued). "Interestingly, we found that Hep55.1C tumor do not express albumin, a liver specific gene, in line with its poorly differentiated state." (PMID 25203629, 2014). "In contrast to the cell lines derived from tumor tissues, DHHs are non-cancerous and retain important functions of primary hepatocytes such as secretion of ALB, glycogen storage, LDL uptake, cytochrome P450 function, and the ability to replace mouse hepatocytes in liver injury mouse models." (PMID 22496645, 2012). "Bovine serum albumin did not inhibit adhesion of tumour cells to HUVECs (data not shown)." (PMID 15700042, 2005). "Furthermore, normal albumin levels have been shown to be lower in women than in men, possibly contributing to the less pronounced and statistically not significant difference in plasma albumin between women with benign lesions and women with BTC in this cohort." (PMID 41504962, 2026). "In addition to being passively accumulated, albumin displays natural tumor affinity via interactions with specific receptors, such as glycoprotein 60 (gp60), on vascular endothelial cells and secreted protein acidic and rich in cysteine (SPARC), which is often overexpressed in tumor cells." (PMID 41489768, 2026). "Furthermore, 177Lu-rhPSMA-10.1 has a higher binding strength to human serum albumin than either 177Lu-PSMA-617 or 177Lu-PSMA-I&T, and this higher binding strength is thought to provide an optimal balance between clearance from healthy organs and preservation of high tumor accumulation." (PMID 40049746, 2025). "In addition, boron uptake when conjugated to albumin could be attributed not only to the EPR effect, but also to an increase in catabolism by the tumor or through other albumin-specific transporters such as gp60 and secreted protein acidic and rich in cysteine (SPARC)." (PMID 37759639, 2023). "Therefore, inflammation-based biomarkers such as C-reactive protein albumin ratio (CAR), platelet-to-lymphocyte ratio (PLR), neutrophil-to-lymphocyte ratio (NLR), and albumin-globulin ratio (AGR) have been used for early assessment of prognosis in a variety of tumours." (PMID 36998452, 2023). "Additionally, because albumin can interact with albondin (gp60 receptor) on endothelial cells, the fusion also facilitated the transport of TRAIL across the endothelium into the tissues via caveolae-mediated transcytosis leading to enhanced tumor-suppressing potential." (PMID 36291908, 2022). "The role of several inflammatory markers such as platelet‐to‐lymphocyte ratio (PLR), CRP, albumin, and NLR have been extensively studied in the context of various malignancies, as these markers might reflect the interaction between the immune system and tumor microenvironment." (PMID 34159754, 2021). "The depletion procedure used in this study was successful, because no albumin nor immunoglobin was detected on the gels, with the exception of immunoglobin heavy chain constant α 1 membrane bound isoform 1, which is recognised as a tumour-related cell membrane protein." (PMID 31622403, 2019). "Hence, both ALB and ALP might play major roles in tumor progression." (PMID 31161711, 2019). "Interestingly, the fusion protein 33A provided higher tumour uptake values compared to other conjugates at as early as 6 h p.i., likely due to elevated fraction of freely circulating 33A (i.e., not bound to albumin) that also leads to more rapid blood clearance." (PMID 30314301, 2018). "Laboratory tests used to identify systemic inflammatory markers such as serum levels of C-reactive protein or albumin may overcome these two problems however, these parameters might be altered in cirrhotic patients with or without tumour disease, therefore their utility is questionable." (PMID 29262546, 2017). "However, whether tumor cells that do not express oncogenic Ras proteins, constituting about 70% of tumors, have compensatory processes to enhance protein (albumin) acquisition is unexplored." (PMID 27974681, 2017).
tumor (continued). "Additionally, pre-albumin, tumor size, and TNM stage were demonstrated to be independent prognostic indicators by multivariate analysis with Cox regression, and the performance of pre-albumin for predicting OS in AEG patients was further identified by ROC curves (P = 0.006)." (PMID 27809860, 2016). "Therefore, molecules such as serum albumin and streptavidin, which balance systemic clearance and diffusion into tumors for maximal EPR effect, may be advantageous if the goal of an experiment is simply tumor detection." (PMID 25901755, 2015). "In this study, six different imaging biomolecules, with or without specificity to tumor, were examined for tumor uptake and internalization at the whole body, ex-vivo tissue, and cellular levels: antibodies, antibody fragments (Fab), serum albumin, and streptavidin." (PMID 25901755, 2015). "In conclusion, this study found preoperative albumin to be a prognostic marker of survival in patients with iCCA and GBC, in both women and men and regardless of tumor resectability." (PMID 41504962, 2026). "Preoperative albumin was prognostic for survival in patients with iCCA and GBC, in both women and men and regardless of tumor resectability." (PMID 41504962, 2026). "The MFP proteome was enriched for several immune-related and plasma proteins more indicative of inflammatory infiltration and chronic immune activation rather than tumor-specific remodeling including C1QB, CFH, MZB1, IGKV3-20, ORM2, ALB, and AZGP1." (PMID 41007761, 2025). "Nevertheless, despite tumor progression, renal remission persisted throughout the subsequent 1.5 years, with no proteinuria (24 h UTP 0.09 g/d), normal serum albumin (38.2 g/L), and stable renal function (eGFR 90.0 mL/min/1.73m2)." (PMID 41244787, 2025). "The addition of parameters based on albumin and CRP, but not dNLR, to a base model including age, chromogranin A, the cell proliferation marker Ki‐67, performance status, tumour site and previous treatments improved the predictive accuracy of the base model." (PMID 38477040, 2025). "Analysis of stage 0–IV patients revealed that serum TNC levels were weakly correlated with the inflammatory markers albumin and NLR and the tumor marker CA19-9 but not with the body composition marker BMI or the tumor marker carcinoembryonic antigen (CEA)." (PMID 38797735, 2024). "It was observed that three key FRGs (ALB, ATF3, and DUSP1), which were differentially expressed between renal tubular tissues with and without FSGS in patients receiving tumor nephrectomy, conformed to the predicted results." (PMID 38368317, 2024). "As a negative control, results also showed that ALB and Hep-Par1 were only expressed in adjacent non-tumor tissue (100%, 3/3) and not in ICC tumor tissue (0%, 0/3)." (PMID 37368186, 2023). "Significant differences were observed in ECOG PS, the histological type, liver metastasis, tumor size, the white blood count, neutrophils (%), lymphocytes (%), sNLR, CRP, and albumin between the groups with or without early death." (PMID 35871700, 2023). "As for other clinical information relevant to surgery, there are no statistical differences between the two groups in tumour location, stoma, operation time, intraoperative haemorrhage, intraoperative blood transfusion, postoperative CRP, and ALB." (PMID 35923439, 2022). "The largest tumor size, advanced BCLC stage, higher INR and TBil, lower albumin, and conservative treatment were negative independent predictors for overall survival." (PMID 36002714, 2022). "The prognostic significance of the CRP/albumin ratio existed in Stages III and IV PC patients and had no connection with the primary tumor location." (PMID 35965580, 2022). "The tumor size, vascular invasion, AST, ALT, and albumin levels, but not AFP levels, were significantly different between both groups (p < 0.001)." (PMID 35455635, 2022).
tumor (continued). "The absence of albumin can lead to immune regulation dysfunction by affecting the stabilized cell growth, DNA replication, and antioxygenation in vivo, and the albumin degradation products may serve as source of nutrient substrates for accelerating tumor growth and proliferation." (PMID 33816284, 2021). "Blood metabolites including low-density lipoprotein (LDL), albumin, total protein, non-esterified fatty acids (NEFA), and glucose were altered by tumor presence or age, in line with an altered metabolic state of the animals." (PMID 35008253, 2021). "After incubation of albumin nanoparticles with HUVEC cells and 4T1 tumor cells, without laser irradiation, IGM showed little toxicity to HUVEC cells, but significantly killed 4T1 cell." (PMID 33407570, 2021). "The current nanoparticle albumin-bound (nab)-technology, such as nab-paclitaxel, uses HSA as a natural solubilizer of insoluble drugs, not as a tumor-targeting carrier." (PMID 34452170, 2021). "An analysis that adjusted for confounding factors showed that initial viable response did not improve the capability of combining tumor staging (BCLC), liver function (albumin) and best overall radiological response to predict overall survival." (PMID 33778924, 2021). "The result showed that albumin level ≥35 g/L and AFP <100 μg/L were independent prognostic factors of HR in intermediate-stage HCC and that tumor size and tumor number were not independent prognostic factors in multivariate analysis." (PMID 33112547, 2020). "Patients with Child grade B had significant poor liver function reserve, such as lower serum albumin, higher ICG R-15, more severe PH, whereas the tumor-related data had no statistic difference in the two subgroups." (PMID 30511133, 2019). "The analyses in the entire cohort revealed that the total bilirubin level, serum albumin levels, and HBV-DNA, but not tumor number, were determined as prognostic factors of survival." (PMID 29765560, 2018). "No statistical differences were noted in age, gender, tumor type, prior treatment, BMI, Hb, total bilirubin, AST, ALT, PT INR, and albumin between the two groups." (PMID 29879960, 2018). "We developed a nano-antibody targeted chemotherapy (nATC) delivery strategy in which tumor specific and clinically relevant antibodies (rituximab, anti-CD20) are non-covalently bound to the albumin scaffold of nab-paclitaxel (ABX)." (PMID 28378801, 2017). "The mean Ct values for the human ALB were much lower than those for the mouse ALB for all 9 PDXs, indicating human DNA was much more abundant than mouse DNA in the PDX tumor tissues (data not shown)." (PMID 26435481, 2015). "Part 2 analyzes tumor and non-target tissue dose-response by 90Y PET quantification and evaluates the accuracy of tumor 99mTc macroaggregated albumin (MAA) single-photon emission computed tomography with integrated CT (SPECT/CT) predictive dosimetry." (PMID 23885971, 2013). "Immunohistochemically, many liver specific proteins, including AFP, albumin, transferin, PIVKA (protein induced in the absence of vitamin K), and alpha-1-antitrypsin, have been detected in the tumor cell cytoplasm." (PMID 21914163, 2011). "However, TM4SF5 mRNA expression was nortably increased in tumor samples from patients with HCC compared with in nontumor samples, unlike ALB mRNA levels." (PMID 40186033, 2025). "Both confluent and proliferating HepaFH3 cells (HepaFH3 C and HepaFH3 P) showed a statistically significant reduction in albumin, hepatocyte nuclear factor 4 alpha (HNF4A), and cytochrome P450 3A4 (CYP3A4) expression compared to non-HCC-PHHs isolated from tumor-free liver tissue." (PMID 40862732, 2025). "Albumin-conjugated MMAE prodrugs exhibited a 7.5-fold higher releaseefficiency under the same irradiation dose compared to nonalbumin-conjugatedprodrugs, significantly inhibiting tumor growth in mice (RABiT-MMAE andRad-Act-NP)." (PMID 40893960, 2025). "PS score, PG-SGA score, tumor stage, PAB, ALB, and BFP did not affect ECW/TBW." (PMID 40842552, 2025).
tumor (continued). "Interestingly, serum albumin, CRP, preoperative tumor markers (CEA and CA19-9), PNI, and mGPS were not significantly different between the SO and non-SO groups." (PMID 39410049, 2024). "177Lu-labeled albumin-binder-conjugated Lys-urea-Aad, Lys-urea-Cmc and Lys-urea-Cms derivatives could further enhance uptake in PSMA-expressing tumor xenografts without significantly increasing uptake in kidneys and salivary glands." (PMID 37649602, 2023). "An erlotinib/hyaluronic acid/human serum albumin complex (ERT-HSA-HA NPs) was developed and tested on tumor cell lines and animal models with promising results, including tumor growth inhibition and lack of recurrence, possibly explained by longer plasma half-life and higher tumor uptake." (PMID 36979684, 2023). "Both tumour markers also showed a positive correlation with the severity of BCLC staging, Child–Pugh score, total bilirubin, ALT and INR levels, and a negative correlation with albumin levels." (PMID 36013482, 2022). "By immunofluorescence, we could readily detect albumin uptake when Panc1 and CFPAC-1 shSOX8 cells were pulsed with 0.5% (w/v) human albumin for 30 min in medium but could not detect albumin in Panc1 SOX8 cells and CFPAC-1 tumor cells." (PMID 35173526, 2022). "The confounding factors, such as gender, age, surgical approach, pTNM staging, tumor site, histological type, EMVI, PNI, CRM, number of lymph nodes examined, hemoglobin, and albumin were well matched in the two cohorts, and none was found to differ significantly between the pairs at baseline." (PMID 35281851, 2022). "However, there were no statistical significance in age, gender, HBsAg, tumor number, alpha-fetoprotein (AFP), vascular invasion, BCLC stage, differentiation, PT, ALT, GGT, and ALB." (PMID 33906632, 2021). "For example, a patient with an albumin of 45 g/L, a bilirubin of 7 μmol/L, an AFP of 5789 U/L, the largest tumour measuring 5.9 cm with macrovascular invasion, but without extrahepatic spread, will have a predicted survival of 87%, 70%, 44% and 19% and 9% at 3, 6, 12, 24 and 36 months, respectively." (PMID 31579990, 2020). "Also, low albumin level was an unfavorable prognostic factor for OS and PFS, whereas poorly differentiated tumor were negative prognostic factor for OS, consistent with results from previous studies." (PMID 32410380, 2020). "Significant differences were found among these 3 therapy groups with respect to median tumor size, BCLC stage, baseline HBV DNA levels, and AFP levels, whereas nonsignificant differences were found in Child-Pugh scores, albumin levels, and Impact-R platelet counts." (PMID 32338753, 2020). "Based on these studies, the levels of pre-EBV-DNA, pre-HGB, pre-ALB, pre-CRP, and pre-LDH have been evaluated in this study, combined with gender, age, T stage, N stage, smoking, drinking history, family history of tumor, and radiotherapy with/without IC or CC." (PMID 33363024, 2020). "Using a red fluorescence protein (RFP)-labeled in vivo tumor model of POCM, the Q3STCy probe provided high sensitivity (96.9%) but modest specificity (61.0%), most likely the result of albumin-probe interactions and non-specific activation in nearby altered but healthy cells." (PMID 28977855, 2017). "In the present study, lower serum albumin levels, higher AST levels, higher serum AFP levels, multinodularity, larger tumor size, the presence of vascular invasion, and noncurative treatment modalities were associated with poorer overall survival in HCC treatment." (PMID 25546689, 2014). "The IP-10 levels only showed a very weak correlation with Albumin-bilirubin (ALBI) score, Child-Pugh score, Branched-chain amino acids (BCAA), Branched-chain amino acids/tyrosine ratio (BTR), platelet counts, alpha-fetoprotein (AFP), and tumor size, with no alternative indicators." (PMID 40373032, 2025).